C12orf71 (chromosome 12 open reading frame 71)
Synonyms: LOC728858
Tractability: No criterion of Open Targets' tractability assessment is met for any kind of drug.
Gene: Protein-coding gene on chromosome 12 (27,081,057 to 27,082,578, reverse strand). Ensembl gene ENSG00000214700.
Subcellular location (Human Protein Atlas): Cytosol
Genetic constraint (gnomAD): Loss-of-function variants: 10 observed, 11.83 expected, observed/expected ratio (o/e) 0.85, 90% interval 0.52 to 1.43. The upper end of that interval is the gene's LOEUF score, 1.43, which puts it in group 5 of 6, group 1 being the genes least tolerant of losing a copy. Missense variants: 289 observed, 316.42 expected, observed/expected ratio (o/e) 0.91, 90% interval 0.83 to 1.01. Synonymous variants: 109 observed, 121.23 expected, observed/expected ratio (o/e) 0.9, 90% interval 0.77 to 1.05.
Homologues: Orthologues: chimpanzee C12H12orf71 (99% identical), macaque C11H12orf71 (90% identical), dog C27H12orf71 (58% identical), rat C4h12orf71 (46% identical), mouse 1700034J05Rik (42% identical).